LEP (leptin)
Diseases named in the same sentence as LEP in open-access papers (continued):
Sharing a sentence is not in itself a finding about the gene and the disease.
Obesity (continued). "Thus, the concomitant increase in expression of gastric CNR1 and LEP in patients with hepatic inflammation seen in this study may be another indication of contribution of peripheral leptin resistance to obesity-associated NASH." (PMID 24716593, 2014). "However, both leptin and hsCRP have been shown to be associated with obesity." (PMID 24727903, 2014). "Thus, leptin and resistin may represent the principal mediators of the impact of obesity on the inflammatory markers involved in cardiovascular risk in T2D patients." (PMID 24736687, 2014). "High levels of IL-1Ra may be linked to the development of obesity-induced leptin resistance, as direct injection of IL-1Ra to the cerebral ventricle can inhibit the suppressive effects of leptin on food intake and blunt leptin mediated increase in core body temperature." (PMID 25244011, 2014). "Whether decreased CNS sensitivity to leptin is a cause or a consequence of obesity is unclear." (PMID 24944902, 2014). "Therefore, one mechanism by which fructose may cause obesity is by failing to elevate glucose levels in the blood to the same levels as other dietary sweeteners after a meal, thereby failing to elicit the same leptin-mediated anorexia." (PMID 25211467, 2014). "Therefore, plasma leptin levels are increased in obesity and decreased after weight loss." (PMID 25136363, 2014). "In addition, obesity caused by leptin may be associated with other lifestyle factors considered bio-behavioral risk factors for depression, and obesity may increase psychological distress and depressive symptoms." (PMID 25061971, 2014). "Since, in both animal and human models of leptin deficiency, infertility is present together with the obesity phenotype, it is to be expected that altered levels and/or function of leptin might be involved in causing infertility in overweight women with PCOS too." (PMID 24895638, 2014). "The high association between obesity and fatty liver disease may result from the serum concentration changes of several important adipokines and one such adipokine is the 16 kDa protein hormone leptin." (PMID 24838072, 2014). "The central leptin gene therapy has also been effective to insulin-deficient diabetes in obesity animal models such as ob/ob mise, diet-induced obese mice, and insulin-deficient type 1 diabetes mice, and in patients with inactivating mutations in the leptin gene." (PMID 23579596, 2013). "Development of novel therapeutic procedures for obesity and obesity-associated diseases possibly could be achieved through an integral insight into leptin, resistin and visfatin, as well as insight into other adipokine functions and their links to inflammation." (PMID 23634778, 2013). "Adipokines (leptin, resistin and visfatin) could serve as a missing link in the causal relationship between psoriasis and comorbidities and may provide a biomarker for disease severity such as obesity and diabetes, risk of comorbidities and treatment success." (PMID 23634778, 2013). "Therefore, serum leptin levels may be considered in conjunction with BMI for identifying obesity associated metabolic disorders." (PMID 24455217, 2013). "Diet-induced obesity resulted in cognitive impairment whose mechanisms are associated with vascular damage to the central nervous system and numerous metabolic abnormalities including dyslipidaemia and glucose intolerance, producing functional resistance to insulin and leptin (diabetes)." (PMID 23741384, 2013). "Finally, leptin may play a crucial role in controlling food intake and consequently preventing overweight and obesity in animals with physiological hyperphagia caused by food restriction and refeeding." (PMID 23372694, 2013). "Therefore, different tumor types could be more or less susceptible to obesity-induced signals, including leptin." (PMID 24202338, 2013).
Obesity (continued). "Moreover, it is believed that leptin level deductions might be the cause of obesity and may play an important role in the development of Type 2 Diabetes Mellitus (T2DM), as well as in cardiovascular diseases (CVD)." (PMID 24051404, 2013). "Obesity is associated with excessive adipose tissue accumulation due to excessive energy intake and insufficient energy expenditure, and is characterized by the alteration of leptin levels, a cytokine produced by adipocytes and one of the regulators of energy metabolism." (PMID 23856194, 2013). "Clinical studies demonstrated a positive correlation between serum leptin levels and left ventricular (LV) mass or wall thickness, independent of blood pressure levels, suggesting a direct role for leptin in the pathogenesis of obesity-associated cardiomyopathy." (PMID 23841921, 2013). "Therefore, leptin stimulation caused by GC promotes “leptin resistant” obesity and, in turn, obesity may contribute to the reduction of cognitive skills observed in AD." (PMID 22701480, 2012). "Also leptin deficient mice have normal or reduced BP, despite severe obesity, suggesting that a functional leptin system may be necessary for obesity to increase sympathetic nerve activity and BP." (PMID 23251471, 2012). "Leptin may be a potential link between obesity and risk of progression of prostate cancer." (PMID 22690216, 2012). "The mechanism(s) whereby a HFD causes leptin resistance and obesity however remain unclear." (PMID 22276206, 2012). "These hypotheses could complement recent findings describing a participation of the NF-κB (nuclear factor ‘kappa-light-chain-enhancer' of activated B-cells) as well as the JNK (c-Jun N-terminal kinase) signaling pathway in the development of ER stress- and obesity-associated leptin resistance." (PMID 22545089, 2012). "Thus, proper insulin action at the level of the adipose tissue is thought to be required for normal metabolic homeostasis, which include the regulation of whole body insulin sensitivity, the susceptibility to obesity, and the relationship between plasma leptin and body weight." (PMID 23024762, 2012). "The dysfunction of these receptors might cause leptin resistance and obesity." (PMID 21631924, 2011). "However, obesity-linked variations of adipokines levels we found were almost comparable to those that predicted the risk of diabetes in adults, and the prognostic role of leptin also as a predictor of weight excess reduction was earlier demonstrated." (PMID 21365005, 2011). "This hypothesis is supported by the observed, in our study, significant positive correlations between BMI and serum concentrations of sTNFR 2 and BMI and leptin in depressive, obese subject, which suggest that the level of obesity is more associated with immune activation than depression." (PMID 19587822, 2009). "The identification of the adipocyte-derived obesity gene product, leptin (Ob), and subsequently its association with reproduction in rodents and humans led to speculations that leptin may be involved in the regulation of oocyte and preimplantation embryo development." (PMID 19835605, 2009). "Importantly, it appears that serum leptin may represent an independent predictor of the severity of illnesses associated with obesity." (PMID 20150963, 2009). "Thus, the intriguing possibility exists that leptin could be directly related to breast carcinogenesis by underlying the effects of obesity on cancer development." (PMID 19223908, 2009). "Since increased BMI and central fat are associated with increased risk for breast cancer in prospective studies, increased leptin exposure associated with obesity and central adiposity could explain the greater incidence of breast cancer in overweight or obese postmenopausal women." (PMID 17229323, 2007). "Among the adipokines tested, leptin, a hormone produced by adipocytes, has the highest sensitivity and statistical ability in relation to hypertension in children suffering from obesity." (PMID 41596212, 2026).
Obesity (continued). "It mainly emphasizes on the impact of obesity and leptin levels on sex-specific pubertal mechanisms." (PMID 41240372, 2026). "Other prominent hormonal mediators in obesity-induced PDAC include leptin, an appetite-suppressing hormone released by adipocytes." (PMID 41484057, 2026). "This renders MCF-7 cells instrumental in investigating hormonal effects on obesity, such as leptin, through modulation of estrogen receptor signaling pathways and tumor growth." (PMID 41562922, 2026). "A study has demonstrated that under high-fat diet-induced obesity, EPAC1 deficiency triggers adipose tissue inflammation and glucose intolerance, accompanied by insufficient leptin secretion and leptin resistance." (PMID 41503874, 2026). "The imbalance between energy intake and expenditure leads to obesity and metabolic changes, such as dyslipidemia, resulting in a reduction in adiponectin levels, an increase in leptin levels, and fatty acids release into the blood circulation." (PMID 41510340, 2026). "By countering the adaptive response by the brain in response to the changes in gut hormone levels and reduction in leptin levels, obesity medications allow for homeostatic adipose mass regulation at a lower calorie intake and adipose mass set point." (PMID 41268722, 2026). "At weaning, male offspring exposed to maternal or combined maternal-paternal obesity showed increased body weight, adiposity and plasma leptin concentrations." (PMID 42285777, 2026). "These microbial changes were correlated with obesity-related metabolic and adiposity markers, including leptin and lipid parameters." (PMID 41901100, 2026). "Leptin levels were assessed to determine the effects of BFL herbal beverages on male rats with obesity." (PMID 41510340, 2026). "Diet‐induced obesity, such as high intake of fats, carbohydrates, fructose, and sucrose, contributes to leptin resistance, which weakens its anorexigenic effect and perpetuates overeating." (PMID 41510340, 2026). "Monogenic forms of severe early-onset obesity often involve genetic disruptions in the hypothalamic leptin-melanocortin pathway." (PMID 41516406, 2026). "Here, we demonstrate that leptin signaling is key to BC progression, particularly in the context of obesity." (PMID 41562922, 2026). "In EPAC2A knockout mice, high-fat diet-induced hypothalamic leptin signalling defects are significantly alleviated, and the animals exhibit enhanced responsiveness to leptin-induced feeding suppression, with a marked reduction in obesity incidence." (PMID 41503874, 2026). "Abstract figure legend Maternal obesity induces systemic inflammation and high insulin and leptin levels, potentially promoting hepcidin release into circulation and thus iron sequestration in specific tissue compartments." (PMID 41275403, 2026). "The vast majority of monogenic forms of obesity are due to genetic defects in the hypothalamic leptin-melanocortin signalling pathway, a pathway crucial in regulating appetite, energy regulation, and body weight." (PMID 41516406, 2026). "Obesity and MetS induce neuroinflammatory and excitotoxic states that promote seizure onset via leptin resistance, reduced adiponectin levels, and compromised AMP-activated protein kinase (AMPK) signaling." (PMID 42072305, 2026). "Taken together, our data suggest that leptin doses mimicking hyperleptinemia in individuals with obesity were able to activate NCOA1, contributing to the activation and phosphorylation of the JAK2/STAT3 pathway." (PMID 41562922, 2026). "In the early stage, we established TRIB1 knockout mice, selected wild-type (WT) and knockout (KO) mice of the same litter and gave them a HFD and berberine treatment, and measured leptin levels and obesity-related phenotypes." (PMID 41588470, 2026). "Similar findings have been reported in other BC cell lines treated with high leptin doses, including MDA-MB-468, HCC-1806, and T47D, suggesting a pivotal role for leptin in BC progression in women with obesity." (PMID 41562922, 2026).
Obesity (continued). "Obesity plays a central role in the pathophysiology of HFpEF, and GLP-1RAs promote weight loss, reduce insulin resistance and leptin signaling, and improve hemodynamic and metabolic abnormalities associated with HFpEF." (PMID 42280332, 2026). "Unsurprisingly however, since leptin has stronger and more direct links to obesity, 401 leptin CpGs were sensitive to BMI adjustment (pfdr>0.05)." (PMID 41057690, 2026). "Our results indicated that elevated leptin levels, reflecting hyperleptinemia seen in obesity, promote cellular proliferation, migration and epithelial–mesenchymal transition (EMT) in BC cells." (PMID 41562922, 2026). "This can in turn exacerbate obesity, increase leptin gene expression, and amplify its level in blood serum." (PMID 41549047, 2026). "In the present study, the administration of BPL herbal beverages in all combinations containing phytochemicals and low energy demonstrated to reduce BW, LI, BFC, TG, and leptin levels in male rats with obesity." (PMID 41510340, 2026). "Elevated AIF-1 levels correlate with inflammatory adipocytes and obesity, while reduced AIF-1 promotes weight loss through regulation of monoamine oxidase A and decreased leptin/resistin production." (PMID 41694567, 2026). "These interactions are further complicated by metabolic conditions such as obesity and diabetes, where hormonal resistance (e.g., leptin, insulin) and neurotransmitter dysregulation contribute to altered taste preferences and compulsive eating behaviors." (PMID 41659336, 2026). "The increases in Cyclin D1 at 100 ng/mL concentrations further emphasize leptin’s role in regulating cell cycle progression, promoting cellular proliferation, and fostering aggressive phenotypes characteristic of obesity-driven cases." (PMID 41562922, 2026). "At the same time, berberine treatment reduced the gene and protein levels of SOCS3 and improved obesity-induced leptin resistance." (PMID 41588470, 2026). "As detailed in Section 3.3, chronic hyperleptinemia in obesity and HFpEF promotes endothelial dysfunction and myocardial fibrotic remodeling, effects that are amplified by acquired leptin resistance." (PMID 41596265, 2026). "Mechanistically, type I inflammatory cytokines and obesity-associated molecules—including IFN-γ, TNF, leptin, insulin, and palmitate—induced PD-1 expression on macrophages through mTORC1- and glycolysis-dependent pathways." (PMID 41551882, 2026). "Research suggests that obesity exerts sex-specific effects on pubertal onset, potentially through leptin regulation." (PMID 41240372, 2026). "The sex-specific differences in leptin levels, characteristic of normal-weight (pre-)pubertal children is lost in obesity." (PMID 41240372, 2026). "In females, body weight at weaning was higher across all parental obesogenic diet groups, and increased adiposity and plasma leptin concentrations were observed in maternal and combined maternal-paternal obesity." (PMID 42285777, 2026). "Conversely, central overactivation of EPAC2A exacerbates leptin resistance, becoming a key driver of obesity." (PMID 41503874, 2026). "Background/Objectives: Obesity is characterized by dysregulated hypothalamic energy homeostasis and reduced central responsiveness to the anorexigenic hormones leptin and insulin." (PMID 41754099, 2026). "Although the number of studies focusing on metabolomics in the context of hypertension in children and adolescents with obesity is limited, the most important adipokines and cytokines affecting the cardiovascular system include adiponectin, leptin, and IL-6." (PMID 41596212, 2026). "Overall, the BPL herbal beverage with an 85:15% ratio exerts its anti‐obesity effect through the inhibition of TG absorption and leptin secretion." (PMID 41510340, 2026). "In obesity and diabetes, its inflammatory transformation results in increased secretion of leptin, resistin, and MCP-1/CCL2, along with diminished adiponectin secretion." (PMID 41596265, 2026).
Obesity (continued). "Participants with obesity had higher leptin and lower adiponectin across all time points (p < 0.001) with both meals." (PMID 42149945, 2026). "Among these, leptin is a pivotal regulator of energy homeostasis and obesity but also plays a prominent role in regulating lipid metabolism by stimulating lipolysis and fatty acid oxidation while downregulating lipogenesis." (PMID 41598432, 2026). "Celastrol, a leptin-sensitizing agent derived from Tripterygium wilfordii, has shown potent anti-obesity effects in rodent models; however, its effects in dogs have not been studied." (PMID 41695210, 2026). "I would like to rephrase it: Furthermore, obesity leads to structural heart changes and HF with reduced ejection fraction (HFrEF) by activating neurohormonal pathways, especially through leptin." (PMID 41597417, 2026). "A high-fat diet contributes to overweight and obesity by stimulating adipose tissue to secrete adipokines such as leptin, adiponectin, resistin, and visfatin." (PMID 40724666, 2025). "Leptin regulates glucose and lipid metabolism, exercise, immune function, and reproduction, and plays an important role in obesity and related metabolic diseases." (PMID 41016636, 2025). "Further studies should investigate the connection between leptin signaling and pulmonary cells, in particular in the context of metabolic disorders like obesity." (PMID 40635334, 2025). "Obesity is associated with elevated levels of IL-6, TNF-α, CRP, and leptin, as well as altered macrophage profiles - all of which contribute to systemic and neural inflammation." (PMID 40909065, 2025). "Our observation of diminished leptin levels parallels rare cases of human obesity resembling the pathophysiology of type I diabetes." (PMID 40565688, 2025). "Mechanistically, this signaling can down-regulate JAK2-STAT3 through the binding of the SH2 domain of suppressor of cytokine signaling 3 (SOCS3) to LepRb Tyr985, contributing to leptin’s anti-obesity effects." (PMID 41251447, 2025). "Leptin and resistin, which are elevated in obesity, further aggravate plaque instability by inducing reactive oxygen species (ROS), smooth muscle cell proliferation, and extracellular matrix remodeling." (PMID 41282294, 2025). "In normal conditions, the secretion of the adipokines, leptin, and adiponectin by adipocytes is inversely correlated, being increased and reduced, respectively, in response to obesity." (PMID 40961178, 2025). "Oxt administration has been extensively investigated for the treatment of obesity in both animal models and humans, with studies also reporting a significant interaction with leptin in the regulation of food intake." (PMID 41016636, 2025). "In instances of obesity, there is an increase in leptin secretion; nonetheless, it is common for individuals to develop resistance to leptin." (PMID 40642747, 2025). "Leptin – a pleiotropic adipokine with diversefunctions – plays an essential role in obesity, IR, inflammation, and hepaticmetabolism, and its levels serve as a gauge of energy stores." (PMID 41165450, 2025). "Air pollution exposure is strongly correlated with impaired insulin signaling, increased leptin resistance, and elevated inflammatory markers in the brain, mirroring physiological changes observed in obesity." (PMID 41515969, 2025). "Specifically, ewes assigned to obesity management treatments exhibited improvements in concentrations of leptin, NEFA, insulin, and urea in plasma, as well as glucose metabolism, in comparison to the obese ewes on both PPD1 and PPD150." (PMID 41463818, 2025). "This was in line with many studies examining the relationship between the LEP rs7799039 polymorphism and MetS, T2DM, and obesity." (PMID 39136228, 2025). "Elucidating leptin's role in lung inflammation, and its interplay with metabolic disorders like obesity, will help designing therapeutical strategies in ARDS." (PMID 40635334, 2025).